KLRK1-AS1 (KLRK1 antisense RNA 1)
Synonyms: LOC101928100; TP53LC04
Gene: Long non-coding RNA gene on chromosome 12 (10,363,608 to 10,398,506, forward strand). Ensembl gene ENSG00000245648.
Diseases named in the same sentence as KLRK1-AS1 in open-access papers:
KLRK1-AS1 is named in the same sentence as 1 disease in open-access papers, as found by Europe PMC text mining. Sharing a sentence is not in itself a finding about the gene and the disease.
KLRK1-AS1 shares sentences with these, for which no sentence is quoted: Tumor (1 paper).